ADAM33 (ADAM metallopeptidase domain 33)
Diseases named in the same sentence as ADAM33 in open-access papers (continued):
Sharing a sentence is not in itself a finding about the gene and the disease.
asthma (continued). "This review aimed to gather, assess, and summarize current knowledge on ADAM33′s role in the pathogenesis, development, course, and severity of asthma as well as its possible role in the diagnosis and treatment of this disease." (PMID 38396994, 2024). "This indicates a possibility of a novel asthma treatment directed toward the inhibition of ADAM33′s activity." (PMID 38396994, 2024). "Genetic analysis associated with the development of asthma and COPD has established several disease susceptibility genes such as ADAM33, and orosomucoid-like 3, which are frequent for both asthma and COPD." (PMID 37656706, 2023). "The researchers suggested that this finding has implications for asthma treatment, as ADAM33 is involved in airway remodeling, a key feature of asthma." (PMID 37299440, 2023). "Many genetic variants associated with risk factors for both asthma and COPD (ADAM33, TNFα, MMP9, TGFβ1, GSTM1, GSTP1) have been identified through genome-wide association studies (GWAS)." (PMID 35629128, 2022). "Adam33 is another target gene expressed in lung fibroblasts; a soluble form of this metalloprotease has been shown to induce asthma-related airway remodeling." (PMID 35920332, 2022). "A prominent example is miR-1303, which regulates the epithelial-derived ADAM33 known to be involved in asthma and related bronchial hyperreactivity." (PMID 36172292, 2022). "We demonstrated robust and prolonged silencing of Adam33, a promising disease target in asthma which is expressed primarily in fibroblasts." (PMID 35920332, 2022). "The relationship between this gene and airway hyperresponsiveness, a major component of asthma, is related to the high level of ADAM33 gene expression in subepithelial fibroblasts and smooth muscle tissue of the lung." (PMID 33922216, 2021). "Among the numerous studies that have examined the role of ADAM33 mRNA and soluble ADAM33 levels, most are limited to patients with asthma." (PMID 34848800, 2021). "ADAM33 expression was demonstrated to increase as asthma severity increases, which responsible to promote airway smooth muscle thickening thus leads to airway remodelling." (PMID 33784348, 2021). "Serum levels of a disintegrin and metalloproteinase domain-containing protein (ADAM)-33 were also increased in the asthma subtype with persistent airflow limitation." (PMID 34204767, 2021). "In three different studies we have reported significant association between many SNPS in ADAM33, GMBS, and FOXO3 genes for asthma and AR." (PMID 32295284, 2020). "ADAM 33, the third underexpressed gene of the ADAM family, has been identified as a susceptibility gene for asthma and chronic obstructive pulmonary disease, and it likely plays a role in stimulating immune function, and remodeling of extracellular matrix." (PMID 33028365, 2020). "Although there are data showing a link between ADAM33 and asthma, the exact role of this gene in the pathophysiology of asthma is not entirely clear." (PMID 30186568, 2018). "ADAM33 is preferentially expressed in airway fibroblasts and smooth muscle cells in patients with asthma." (PMID 30186568, 2018). "The minor allele at two of the SNPs showed association with protection from asthma, rs1131882 in TBXA2R gene (OR 0.73, 95% CI 0.52–1.01, P = 0.05) and rs2280091 in the ADAM33 gene (OR 0.69, 95% CI 0.50–0.97, P = 0.03)." (PMID 29588858, 2018). "Using this method, six novel genes, which are closely related to asthma, have been identified, namely, ADAM33, VDR, DPP10, PHF11, HLA-G, and GPR15." (PMID 29751569, 2018). "ADAM33 (ADAM Metallopeptidase Domain 33) is an asthma susceptible gene, and is associated with asthma and bronchial hyper-responsiveness." (PMID 28876365, 2017). "Another candidate gene ADAM33, expressed in ASM, has been shown to be associated with asthma in linkage analysis." (PMID 29228930, 2017).
asthma (continued). "In future studies, we will test these sequences in mouse models to further explore the role of ADAM33/Adam33 in asthma and the potential for oligonucleotides to play a therapeutic role in its treatment." (PMID 28918018, 2017). "To explore the biological role of ADAM33/Adam33 in asthma progression, we have developed a series of mouse models." (PMID 28918018, 2017). "Our work confirms that ASO-based gene silencing of ADAM33 is a useful tool for asthma research and therapy." (PMID 28918018, 2017). "Our data indicated that risk alleles located in ADAM33 rs2280090 and rs3918396, IL4 rs2243250 and CD14 rs2569190 are associated in allergy, asthma, and other related phenotypic traits such as wheezing and atopy." (PMID 27624002, 2016). "ADAM33 is mainly expressed in airway smooth muscle, fibroblasts, and mesenchymal progenitor cells, with each playing a role in asthma-related airway remodeling." (PMID 27489884, 2016). "These revealed a handful of genes, that is, ADAM33, DPP10, PHF11, GPRA, CYFIP2, HLAG, and PTGDR, to be closely associated with asthma." (PMID 27293973, 2016). "Our current data also show that there was a concomitant suppression of ADAM-33, LIGHT, and LTBR, three other mediators known to be associated with the pathogenesis of asthma." (PMID 25642424, 2015). "Polymorphisms in ADAM33, ORMDL3/GSDMB and IL4 were associated with childhood asthma in a group of children with recurrent wheeze." (PMID 25768087, 2015). "We demonstrated association of ADAM33, IL4 and ORMDL3/GSDMB gene polymorphisms with childhood asthma." (PMID 25768087, 2015). "They designed a case-control study with 50 asthmatic patients and 50 age- and sex-matched healthy controls to examine the relationship between the CpG methylation of the ADAM33 gene and asthma using bisulfite deoxyribonucleic acid modification and sequencing." (PMID 24817794, 2014). "A disintegrin and metalloprotease 33 (ADAM33), a member of the ADAM (a disintegrin and metalloprotease) family, has been identified as an asthma susceptible gene." (PMID 25369941, 2014). "This was further supported by a very recent study by investigating the methylation patterns of ADAM33 in adult asthma." (PMID 24817794, 2014). "Over the last few years, a significant progress has been made in understanding the role of a disintegrin and metalloproteinase 33 (ADAM33) in asthma." (PMID 24817794, 2014). "Among these genes, a disintegrin and metalloprotein-33 (ADAM33), the first asthma candidate gene identified by positional cloning on human chromosome 20p, is important in asthma and bronchial hyperresponsiveness." (PMID 24141861, 2013). "There were only five ADAM33 SNPs identified with statistically significant differences between the asthma group and the control group in genotype distribution (P<0.05)." (PMID 24141861, 2013). "Positional cloning and linkage analysis studies of AHR have identified two well-validated asthma candidate genes: ADAM33 and PCDH1." (PMID 23984888, 2013). "We confirmed that the coverage of published GWAS for asthma performed in European populations to date has been insufficient for ADAM33 (<30%), even in a best-case scenario using the HapMap phase 2 data as a reference for comparisons." (PMID 24039878, 2013). "This study evaluated 8 of these genes (IL4, IL13, TNF-α, HLA-DRB1, HLA-DQB1, FCER1B/MS4A2, CD14, ADAM33) as well as 3 glutathione-s-transferase genes (GSTM1, GSTP1, and GSTT1) for association with asthma/allergy among urban-residing African Americans." (PMID 21320344, 2011). "Because the fixed-effect model is more precise than random effect model, the strength of evidence of ADAM33 T1-C/T, ACE D/I, IL-13 -1923C/T, RANTES -28C/G, as risk factors for asthma was greater than that of FcεRIβ -6843G/A, IL-13 -2044A/G and TNF-α -308G/A." (PMID 20868478, 2010).
asthma (continued). "Up to date, we first found that ADAM33 T1-C/T, ACE D/I, IL-13 -1923C/T, RANTES -28C/G and IL-13 -2044A/G polymorphisms were associated with risk of asthma in Chinese population by using meta-analyzes." (PMID 20868478, 2010). "SNPs in the genes ADAM33 (rs528557, p = 0.000019) and VDR (rs1540339, p = 0.0014), previously associated with asthma, were also associated with asthma in this dataset at a significance level of 0.0035 corrected for multiple testing." (PMID 21103062, 2010). "For ADAM33, NPSR1, and CYFIP2, the associations with asthma or asthma-related phenotypes have been studied in East Asian populations such as Chinese and Japanese." (PMID 19951440, 2009). "The ADAM33 gene is expressed in airway smooth muscle cells and fibroblasts in the lung, suggesting that it is not only important in the development of asthma but also in disease progression, possibly through airway remodeling." (PMID 20003279, 2009). "Actually, the associations of ADAM33, NPSR1, and CYFIP2 with asthma or asthma-related phenotypes have been studied in Chinese or Japanese populations." (PMID 19951440, 2009). "Variation in ADAM33 has been shown to be important in the development of asthma and altered lung function." (PMID 19284602, 2009). "Six asthma candidate genes, ADAM33, NPSR1, PHF11, DPP10, HLA-G, and CYFIP2, located at different chromosome regions have been positionally cloned following the reported linkage studies." (PMID 19951440, 2009). "Lee and coworkers demonstrated that ADAM33 protein levels in bronchoalveolar lavage fluid (BALF) are inversely correlated with predicted FEV1 values in patients with asthma." (PMID 20003279, 2009). "Taken together, these findings suggest an important role for ADAM33 in airway remodelling and asthma." (PMID 18778489, 2008). "Therefore, although the genetic variants do not indicate a clear mode of action for therapy, the classification results do warrant further exploration of ADAM33 as potential target for Asthma or COPD." (PMID 40110561, 2025). "In asthma, airway obstruction results primarily from hyperresponsiveness, eosinophilic inflammation, and excessive tissue remodeling, and increased ADAM33 activity may exacerbate these processes, worsening airflow limitation." (PMID 41373738, 2025). "Deployment of our classification pipeline showed that the top five most occurring effects having a strong relation (classification level 2) with ADAM33 were asthma, chronic obstructive pulmonary disease (COPD), lung function, allergic rhinitis, and airway remodelling." (PMID 40110561, 2025). "Analyzing additional SNPs in STAT6 (e.g., rs324015, rs3024944, rs71802646) and other genes (e.g., IL1RL1, GATA3, ADAM33, TSLP, FOXO3a) would expand the scope of genetic analysis and provide a comprehensive understanding of asthma susceptibility in the population." (PMID 40375219, 2025). "Many genes have been identified as associated with asthma but none with such substantial significance as the ADAM33 gene due to its role in airway remodeling and bronchial hyperresponsiveness." (PMID 38396994, 2024). "Additionally, we discuss the potential clinical implications of ADAM33 as a therapeutic target for asthma management." (PMID 38396994, 2024). "ADAM33 has been a promising target in research and therapeutic applications in asthma management." (PMID 38396994, 2024). "A study from North India showed a haplotype association between ADAM33 and asthma, but the SNPs they studied did not include the SNPs rs2853209 and rs3918396 evaluated in this study." (PMID 36766510, 2023). "Many of the studies did not observe a significant difference between various ADAM33 polymorphisms and asthma." (PMID 36766510, 2023). "Other studies have shown that vitamin D inhibits VEGF-induced respiratory smooth muscle cell proliferation by suppressing VEGFR2 and ERK1/2 activation and downregulation of ADAM33, which may be crucial in developing therapies for diseases such as asthma." (PMID 37174726, 2023).
asthma (continued). "The first report on genes involved in asthma pathogenesis and airway hyperresponsiveness, other than those concerning non-immune and non-allergic pathways, addressed the positionally cloned asthma and bronchial hyperresponsiveness gene ADAM33." (PMID 36766510, 2023). "Interestingly, studies in endobronchial biopsies derived from patients with asthma reveal an increase in the expression of certain genes involved in asthma progression such as disintegrin and metalloprotease (ADAM) 33, ADAM8, eotaxin, and CCL19 in ASM layer." (PMID 36012240, 2022). "In addition, the pulmonary expression of ADAM33 is related to the severity of asthma and airway remodeling." (PMID 36091328, 2022). "Regarding the frequency of the ADAM33 haplotype, we found that the T1 (A), T2 (G), T + 1 (G), V4 (C), S1 (C), S2 (G), Q-1 (G) ADAM33 haplotype was the most common haplotype among adults and children healthy and asthma subjects." (PMID 33922216, 2021). "Over 100 SNPs of the ADAM33 gene have been correlated with asthma." (PMID 33922216, 2021). "The first strong genetic evidence suggesting that genes in non-allergic, non-immune pathways may play important roles in asthma pathogenesis was the report of ADAM33 as the first positionally-cloned asthma gene." (PMID 29588858, 2018). "The lack of association between ADAM33 polymorphisms and asthma was also reported in Australian, Chinese Li, Korean, Indian, and Turkish populations." (PMID 30186568, 2018). "Importantly, ADAM33 expression positively correlated with cell traction force, stiffness, and expression of F-actin and vinculin, suggesting that ADAM33 is a mediator of ASM cell dysfunction in asthma." (PMID 28056993, 2017). "If ADAM33 has a similar capacity for cytokine or growth factor cleavage this could make it a major contributor to airway remodeling in asthma." (PMID 29228930, 2017). "Indeed, ADAM33 expression was significantly higher in the airways of human subjects with asthma compared to those of controls." (PMID 28056993, 2017). "There was no consistent opinion to explain the effect of ADAM33 polymorphisms on asthma in children." (PMID 28876365, 2017). "Although ADAM33 was not yet confirmed by large GWAS as risk locus for allergy and asthma, polymorphisms in this gene are associated with bronchial hyperresponsiveness (BHR), asthma, and allergy across different populations." (PMID 27624002, 2016). "Allergen-induced asthma-like changes are inhibited in Adam33–/– mice." (PMID 27489884, 2016). "Finally, we show that sADAM33-induced airway remodeling is reversible, highlighting the therapeutic potential of targeting ADAM33 in asthma." (PMID 27489884, 2016). "Furthermore, using an ADAM33-specific fluorescence resonance energy transfer (FRET) peptide cleavage assay, ADAM33 enzymatic activity was increased in asthma." (PMID 27489884, 2016). "In addition, expression of RARRES2, CD44 and ADAM33, genes known to contribute to the pathophysiology of asthma, were found to be inhibited in miR-708-transfected cells." (PMID 26998837, 2016). "In addition, miR-708 also caused downregulation of expression of several ‘asthma-related’ genes such as CD44, ADAM33 and RARRES2." (PMID 26998837, 2016). "Polymorphisms in ADAM33 (rs511898 and rs528557) and ORMDL3/GSDMB (rs7216389) were negatively associated and polymorphisms in IL4 (rs2070874 and rs2243250) were positively associated with childhood asthma." (PMID 25768087, 2015). "In an independent birth cohort study we were able to replicate the significant negative association of the CG/GG-genotype of ADAM33 rs528557 with childhood asthma at age six." (PMID 25768087, 2015). "In an independent birth cohort we were able to confirm the negative association of ADAM33 rs528557 CG/GG-genotype with progression of recurrent wheeze into childhood asthma rather than with the presence of wheeze." (PMID 25768087, 2015).
asthma (continued). "Importantly, ADAM33 expression was positively correlated with cell stiffness, traction force, and expression of vinculin and Factin, suggesting that ADAM33 is a mediator of ASMC dysfunction in asthma." (PMID 24817794, 2014). "So far, there have been 4 studies on the ADAM33 DNA methylation and asthma." (PMID 24817794, 2014). "ADAM33 protein has been proposed to contribute to the remodeling process present in asthma and BHR." (PMID 24751681, 2014). "Indeed, increased expression of ADAM33 was detected in human airway from subjects with asthma as compared to that in controls." (PMID 24817794, 2014). "This, in turn, will unlock the possibility of ADAM33 as a target for asthma therapy." (PMID 24817794, 2014). "As these two ADAM33 SNPs have been demonstrated to be correlated with asthma in the study population, they may demonstrate a genetic basis for the association between asthma and the palm dermatoglyphic pattern." (PMID 24141861, 2013). "In this study, we have comprehensively analyzed the association of 286 common variants of eight candidate genes with asthma and atopic asthma in a case-control Spanish sample and found associations for 10 SNPs in three of them (MS4A2, IL4R and ADAM33) after considering all tests performed." (PMID 24039878, 2013). "Therefore, the advantages of taking into account the age at diagnosis varying effects for replication studies in asthma were clearly evidenced in ADAM33, a gene for which SNP-level replications are scarce in the literature." (PMID 24039878, 2013). "Among them, seven polymorphisms (ADAM33 T1-C/T, ACE D/I, FcεRIβ -6843G/A, IL-13 -1923C/T, IL-13 -2044A/G, RANTES -28C/G and TNF-α -308G/A) were statistically associated with increased risk of asthma." (PMID 20868478, 2010). "ADAM33, FcεRIβ, RANTES, TNF-α, ACE, β2-AR, IL-4R and IL-13 genes could be proposed as asthma susceptible genes in Chinese population." (PMID 20868478, 2010). "Additionally, immunostaining for ADAM33 was increased in the epithelium, submucosal cells, and smooth muscle in severe asthma compared with mild disease and controls and in bronchial bud during airway morphogenesis." (PMID 19284602, 2009). "These latter findings suggest a function of ADAM33 related to lung growth and repair in general rather than solely associated with asthma." (PMID 20003279, 2009). "While a number of studies have replicated this finding showing that ADAM33 is a susceptibility gene for asthma in different populations, some studies have not replicated these findings." (PMID 19284602, 2009). "An argument to speculate for a possible key role of ADAM-33 in asthma physiopathology is the increased ADAM-33 expression reported after stimulation by some Th2 cytokines (IL-4 and IL-13)." (PMID 20034386, 2009). "In previous association studies of ADAM33 and asthma/asthma-associated phenotypes, no single ADAM33 SNP was consistently associated with asthma or intermediate phenotypes." (PMID 18778489, 2008). "ADAM33 was the first gene identified in asthma by positional cloning." (PMID 18560587, 2008). "In the present study, adult asthma was associated with ADAM33 SNPs, V4, T2, T1, and Q-1, but not with the T+1 and S1, and the V4, T+1, and T1 sites were also found to have significant associations with AR after correction for multiple tests." (PMID 18778489, 2008). "They showed that no single SNP was associated with childhood asthma in Caucasians, but that a common haplotype of ADAM33 was associated with the disease." (PMID 18778489, 2008). "The identification of a pleiotropic effect of ADAM33 on asthma and psoriasis may contribute to the understanding of these common immune-mediated diseases." (PMID 18560587, 2008). "Because airway remodeling and hyperresponsiveness may overlap between CF and asthma, it is not possible to fully determine whether the observed associations with ADAM33 reflect CF-specific mechanisms or concomitant airway disease resembling asthma." (PMID 41373738, 2025).